TRPC3 (transient receptor potential cation channel subfamily C member 3)
Diseases named in the same sentence as TRPC3 in open-access papers (continued):
Sharing a sentence is not in itself a finding about the gene and the disease.
epilepsy (8 papers, 2014 to 2025). A brain disorder characterized by episodes of abnormally increased neuronal discharge resulting in transient episodes of sensory or motor neurological dysfunction, or psychic dysfunction. "Given the long-postulated role of BDNF in epileptogenesis, TRPC3 channels may be a critical component underlying the pathophysiology of seizures and epilepsy." (PMID 39408863, 2024). "TRPC3 expression is believed to be increased in the hippocampi of rats with pilocarpine-induced epilepsy." (PMID 39513854, 2024). "While all TRP channels regulate cations in some regard, TRPC3 uniquely mediates low Mg2+ and Ca2+ depolarization contributing to epilepsy." (PMID 36902145, 2023). "Expression of several TRPC channels is consistently seen to have an impact on chronic epileptic conditions, and TRPC3 uniquely mediates low Mg2+ and Ca2+ depolarization, contributing to epilepsy." (PMID 36902145, 2023). "TRPC3 and TRPC6 have been suggested to play contrasting roles in excitoxicity in a seizure induction model of epilepsy, with TRPC3 upregulated and TRPC6 downregulated in the hippocampus after pilocarpine-induced seizure." (PMID 34489621, 2021). "Since TRPC3 is a downstream effector of BDNF-trkB signaling pathway that is thought to play a role in epilepsy, one would expect that TRPC3 should play a significant role in pilocarpine-induced seizures and neuronal cell death." (PMID 24722470, 2014). "Inhibition of TRPC3 reduces pilocarpine-induced seizures in mice, which raises the possibility that TRPC3 inhibition could be a novel intervention for seizure disorders." (PMID 37759438, 2023). "Among the TRPC families, TRPC3 is the most reviewed within the setting of epilepsy." (PMID 36902145, 2023). "The finding that VSMC-expressed TRPC3 channels contribute to seizure-induced IHR may have broad implications not only for seizure disorders, but also for other neurological disorders with a component of neurovascular dysfunction." (PMID 31964991, 2020).
diabetes (7 papers, 2012 to 2025). "Additionally, we propose further investigation into the pathogenic role of TRPC3 in other high-prevalence urological complications, including diabetes-associated bladder fibrosis, bladder outlet obstruction-induced fibrotic remodeling, and ketamine-induced bladder fibrosis." (PMID 40271070, 2025). "The most striking aspect of our findings is that the pharmacological activation of TRPC3 alleviates diabetes hallmarks in treated animals." (PMID 36642838, 2023). "Subsequently, TRPC3 activation through targeted small‐molecule enhances insulin secretion and alleviates diabetes hallmarks in animals." (PMID 36642838, 2023). "These insights strengthen one's knowledge of insulin secretion physiology and set forth the TRPC3 channel as an appealing candidate for drug development in the treatment of diabetes." (PMID 36642838, 2023). "These insights into pancreatic TRPC3 function are considered as an essential step toward a better understanding of the intricate insulin secretion physiology and pave the way for the development of promising diabetes‐focused treatments." (PMID 36642838, 2023). "Microarray analysis of the PBMC dataset (Cohort 1), identified FcER1, TRPC3, SNX20, FAM20A, and SLC12A7 as genes showing increased expression with the severity of diabetes." (PMID 34925339, 2021). "This study demonstrates that TRPC3 is significantly upregulated in diabetic dermal fibroblasts, which aligns with previous findings suggesting that TRPC channels are involved in pathological conditions, including diabetes." (PMID 40370935, 2025).
renal fibrosis (7 papers, 2019 to 2025). A final common manifestation of a wide variety of chronic kidney diseases characterized by glomerulosclerosis and tubulointerstitial fibrosis. "Augmented TRPC3-dependent influx was further linked to the increased phosphorylation of the extracellular signal-regulated kinase 1/2 (ERK1/2) to stimulate fibroblast proliferation leading to renal fibrosis." (PMID 32787494, 2020). "TRPC3 is highly homologous to TRPC6 and TRPC3 KO mouse also displayed attenuated renal fibrosis in a UUO mouse model." (PMID 32719603, 2020). "Genetic ablation of TRPC3 has been shown to attenuate renal fibrosis in UUO mouse model." (PMID 32719603, 2020). "TRPC3−/− mice exhibit diminished renal injury, inflammation, and protection against UUO-induced renal fibrosis." (PMID 36277193, 2022). "The potential role of TRPC3 and TRPC6 in renal fibrosis has been studied in an animal model of UUO induction, and both of them are upregulated in the obstructed kidney." (PMID 36277193, 2022). "Pharmacological blockade of TRPC6 ortholog, TRPC3, inhibits fibroblast proliferation and myofibroblast differentiation and genetic ablation of TRPC3 attenuates UUO-induced renal fibrosis in mice." (PMID 32719603, 2020). "The mechanistic link was provided between hypercalciuric conditions, alkalinuric conditions, and the exacerbation of renal fibrosis and inflammation, particularly in the absence of TRPC3." (PMID 38732005, 2024). "Overall, the understanding of TRPC3 and TRPC6 in renal fibrosis pathogenesis has expanded in recent years and may facilitate the development of emerging therapeutic strategies." (PMID 36277193, 2022). "TRPC3 blockade in rats and TRPC3 knockout in mice inhibited ERK1/2 phosphorylation and fibroblast activation, as well as myofibroblast differentiation and extracellular matrix remodeling in obstructed kidneys, thus ameliorating tubule-interstitial damage and renal fibrosis." (PMID 32787494, 2020). "Lastly, both TRPC3 and TRPC6 mRNA were potently upregulated in interstitial fibroblasts of obstructed kidneys, but combined TRPC3 and TRPC6 knockout in UUO provided no additional protection from renal fibrosis compared to TRPC6 knockout mice." (PMID 31877991, 2019).
glioma (6 papers, 2020 to 2024). A benign or malignant brain and spinal cord tumor that arises from glial cells (astrocytes, oligodendrocytes, ependymal cells). "In our present study, the results showed that the expression of TRPC1 and TRPC3 was significantly increased in glioma with IDH mutation status and 1p/19q codeletion status, while the expression of TRPC6, MCOLN1, MCOLN2, and MCOLN3 was significantly decreased." (PMID 35625048, 2022). "TRPC3 levels are associated with both diagnostic and prognostic values: high-grade gliomas have higher TRPC3 expression levels than normal brain tissues, and glioma patients with high TRPC3 expression have a shorter survival time than patients with a lower TRPC3 expression." (PMID 34458247, 2021). "Expression levels of TRPGs were found to differ significantly between normal and glioma tissues, except for TRPC3 and TRPC7." (PMID 38948951, 2024). "Higher levels of TRPC1, TRPC3, and TRPC5 were significantly associated with longer OS time in glioma." (PMID 35625048, 2022). "Reduced proliferation was demonstrated in vitro in U87MG glioma cells with a reduced expression of TRPC3." (PMID 34458247, 2021). "Among the eight final identified hub genes, higher expression levels of TRPC1, TRPC3, and TRPC5 were significantly associated with longer OS time in glioma, while higher expression levels of TRPC4, TRPC6, MCOLN1, MCOLN2, MCOLN3 were significantly associated with shorter OS time." (PMID 35625048, 2022). "The results of the spheroid model showed that the genes TRPC3, TRPC4, TRPC5, and TRPV1 were upregulated in glioma cells either wild‐type isocitrate dehydrogenase 1 (IDH1) or the IDH1 R132H mutant, with or without NaCl treatment." (PMID 39189437, 2024). "In previous reports, TRPC1, TRPC3, TRPC6, TRPML1, and TRPML2 were proven to play crucial roles in glioma progression." (PMID 35625048, 2022). "Consistent expression of TRPC1, TRPC3, TRPC5, and TRPC6 has been found in glioma cell lines and acute patient-derived tissues, which gives rise to small, nonvoltage-dependent cation currents and contributes to the resting conductance of glioma cells." (PMID 32963700, 2020). "The gene expression levels of TRPC1, TRPC3, and TRPC5 were significantly higher in low-grade glioma (LGG), while the levels of TRPC4, TRPC6, TRPM7, MCOLN1, MCOLN2, and MCOLN3 were significantly higher in high-grade glioma (HGG)." (PMID 35625048, 2022).
lung carcinoma (6 papers, 2013 to 2024). "In 2016, a researcher from Guangzhou Medical University validated the effects of TRPC3 variants on lung cancer risk." (PMID 35155435, 2022). "The expression of TRPC1, 3, 4, 6 in lung cancer has been detected and the association of TRPC3 expression with the prognosis of lung adenocarcinoma has been described." (PMID 23840757, 2013). "TRPC3, as a driver gene at both genomics and transcriptomics levels have also been recognized as a promising clinical biomarker for lung cancer, indicating the clinical significance of such multi-omics biomarker." (PMID 35155435, 2022). "TRPC3/C6 channels are highly expressed in certain tumour cells, including lung cancer cells." (PMID 38621757, 2024). "TRPC3 (ENSP00000368966), as another novel driver gene associated with lung cancer at genomics and transcriptomics levels, has been validated to be potential genomic and transcriptomic driver for lung cancer." (PMID 35155435, 2022). "In this study, we have shown that TRPC1, TRPC3, TRPC4 and TRPC6 exist in human lung cancer including the adenocarcinoma, squamous cell carcinoma and the adenocarcinoma-derived cell line A549." (PMID 23840757, 2013). "In conclusion, we found that TRPC1, TRPC3, TRPC4 and TRPC6 channels are expressed in lung cancer." (PMID 23840757, 2013). "Linear multivariance regression analysis also showed a negative correlation of the mRNA expression of TRPC1, TRPC3, TRPC4 and TRPC6 to lung cancer differentiation grade with standardized β coefficient sequence of TRPC1 (−0.563)>TRPC4 (−0.360) >TRPC6 (+0.271) and TRPC3 (−0.057), respectively." (PMID 23840757, 2013). "On the contrary, over-expression of TRPC1 and TRPC6 increased the A549 proliferation, however the effect of overexpression of TRPC3 and TRPC4 has not achieved significance in the lung cancer cells." (PMID 23840757, 2013).
prostate carcinoma (6 papers, 2008 to 2025). A carcinoma that arises from epithelial cells of the prostate gland. "Of note, the effects of conditioned medium from OIS cells on prostate cancer cell proliferation were almost completely abolished by rescue of TRPC3 expression." (PMID 35177596, 2022). "In prostate cancer, TRPC3 was found to promote angiogenesis, which plays a critical role in cancer progression." (PMID 35870973, 2022). "We analysed the expression of TRPC3 in human prostate cancer tissues using published microarray datasets obtained from chemo/radiotherapy-treated patients." (PMID 35177596, 2022). "To verify whether modification of the SASP caused by TRPC3 downregulation could contribute to the acquisition of a chemotherapy-resistant phenotype, we assessed the effect of SASP secreted by CAFs on prostate cancer cells." (PMID 35177596, 2022). "However, TRPC3/C6 channels are highly expressed in certain cancer cells, including lung, ovarian, and prostate cancer cells, and may exert specific functions that are yet to be comprehensively elucidated." (PMID 38621757, 2024). "Copy number alterations were also observed rarely with the exception of the amplification of TRPA1, which was amplified in 7.2% of prostate cancers in TCGA, and of TRPC4 and TRPC3, which were homodeleted in 5.9% and 2.5% of cases, respectively." (PMID 40332161, 2025). "Similarly, in the MSK cohort, TRPA1 was amplified in 6.3% of prostate cancers and TRPC4 and TRPC3 were homodeleted in 4.4% and 1.5% of cases, respectively." (PMID 40332161, 2025). "The prostate cancer cell line (LNCaP) was used as a positive control for TRPC3 and a negative one for TRPC6." (PMID 18452628, 2008). "Based on the observed findings, L687 may be effective as a drug delivery system (DDS) for the selective delivery of ASO to lung or prostate cancer tissues, given that L687 was thought to promote the selective uptake of ASO in cells with high TRPC3/C6 expression." (PMID 38621757, 2024).
triple-negative breast carcinoma (6 papers, 2019 to 2025). An invasive breast carcinoma which is negative for expression of estrogen receptor (ER), progesterone receptor (PR), and human epidermal growth factor receptor 2 (HER2). "TRPC3 is frequently overexpressed in triple-negative breast cancer (TNBC), where it drives proliferation and chemoresistance via the TRPC3–RASA4–MAPK (TRP3-Ras GTPase-activating protein 4-MAPK) axis." (PMID 40806720, 2025).
Arrhythmia (5 papers, 2014 to 2020). Any cardiac rhythm other than the normal sinus rhythm. "Like its DAG-sensitive relatives TRPC6 and TRPC7, TRPC3 has been implicated in a wide array of pathologies and disorders ranging from tumors to cardiac arrhythmias." (PMID 30037143, 2018). "TRPC3 has also been linked to other arrhythmia conditions in addition to AF." (PMID 33013458, 2020). "Recent evidence suggests that Ca2+ entry through TRPC3 (Transient Receptor Potential Canonical-3) channels may underlie several pathophysiological conditions -including cardiac arrhythmias." (PMID 25859221, 2015). "Spontaneous AP events via SOCE-activation were found to be reduced in a TRPC3 knockout mouse model, while excessive activation of TRPC3 has been shown to result in Ca2+ overload and arrhythmias." (PMID 33013458, 2020). "TRPC3 was identified as a crucial player in the proliferation and differentiation of fibroblasts in the myocardium and its activity was found to promote fibrosis, structural remodeling and arrhythmias, specifically atrial fibrillation." (PMID 30037143, 2018). "In this article we will first briefly review TRPC3 and IP3R signaling that relate to store/receptor-operated Ca2+ entry (SOCE/ROCE) mechanisms and cardiac arrhythmias." (PMID 25859221, 2015). "We previously demonstrated that the protein levels of TRPC3 and 6 are increased in Gαq-TG hearts and suggested that the activation of TRPC channels participates in the generation of cardiac arrhythmia induction." (PMID 25171374, 2014).
gastric cancer (5 papers, 2021 to 2024). A primary or metastatic malignant neoplasm involving the stomach. "A recent study showed that TRPC3 is upregulated in gastric cancer (GC) patients and cell lines." (PMID 37507867, 2023). "TRPC3— a role for TRPC3 in TGFβ-induced EMT was described in gastric cancer cells, one mediated via the Ras/Raf1/ERK1/2 signaling cascade." (PMID 34360952, 2021). "Together with TRPC1 and TRPC3, a role for TRPC6 in TGFβ-induced EMT was described in gastric cancer cells, mediated via the Ras/Raf1/ERK1/2 signaling cascade." (PMID 34360952, 2021). "In gastric cancer (GC), the transient receptor potential canonical 3 (TRPC3) promotes tumorigenesis via the CNB2/GSK3β/NFATc2 signaling pathway; thus, TRPC3 could be a possible target for therapeutic intervention." (PMID 39822413, 2024).
Hypercalciuria (5 papers, 2020 to 2024). "This argues for a cytoprotective function of the CaSR-dependent TRPC3 activation as the SOCE-associated downstream cascade of injuring events following hypercalciuria is diminished." (PMID 36613622, 2022). "In a mouse model of TRPC3 ablation, increased hypercalciuria resulted in heightened oxidative stress, precipitating PT cell injury and ultimately forming mixed stones." (PMID 39346653, 2024). "It is noteworthy that TRPC3 knockout mice exhibited hypercalciuria and microcalcification, demonstrating the protective role of TRPC3 in preventing kidney stone formation." (PMID 39346653, 2024). "In contrast, TRPC3 is a protective player in hypercalciuria, while its upregulation and deleterious role have been demonstrated in autosomal dominant polycystic kidney disease-like conditions." (PMID 36613622, 2022). "The critical role of TRPC3 in Ca2+ reabsorption is supported by the development of hypercalciuria after TRPC3 knockout." (PMID 36613622, 2022). "Since proximal tubular injury and the crystal formation were exacerbated by TRPC3 deficiency, it is legitimate to attribute a preventive role to TRPC3 in hypercalciuria-induced crystal formation and tubular injury by reabsorption of excess luminal calcium." (PMID 36613622, 2022). "TRPC3 knockout mice exhibited hypercalciuria and microcalcifications arguing for a protective role of TRPC3 in preventing nephrocalcinosis (renal stone formation)." (PMID 32787494, 2020). "In summary, TRPC3 is critically involved in Ca2+ reabsorption in the proximal tubule and its impaired expression can contribute to hypercalciuria and through crystal formation and calcification support both fibrosis and inflammation which can result in acute and chronic kidney disease." (PMID 36613622, 2022). "We have also shown that the TRPC3-knockout (KO) mice had a phenotype of elevated urinary Ca2+ with CaP crystals in the loop of Henle (LOH), which exhibited moderate hypercalciuria." (PMID 38732005, 2024).
Myocardial fibrosis (5 papers, 2019 to 2023). "Genetically knocking out TRPC3 attenuated myocardial fibrosis in pressure-overloaded HF mice." (PMID 34204537, 2021). "Meanwhile, TRPC3 channel is an indispensable regulator of fibrosis development, by promoting fibroblasts to transition into myofibroblasts via intracellular Ca2+ overload, and it plays an important role in the process of myocardial fibrosis." (PMID 31772600, 2019). "Recently, TRPC3 channel was identified as a mediator of myocardial fibrosis." (PMID 31871548, 2019). "In an AF dog model, TRPC3 was found to regulate the proliferation of myocardial fibrosis by affecting Ca2+ influx through the MAPK1/miRNA-26/NFAT pathway, thereby increasing the expression of TRPC3 in the myocardium." (PMID 34257520, 2021).
pulmonary arterial hypertension (5 papers, 2016 to 2026). Pulmonary arterial hypertension (PAH) is a group of diseases characterized by mean pulmonary artery pressure >20 mmHg and elevated pulmonary arterial resistance leading to right heart failure. "Considering the vasodilatory and proliferative effects of EtbR, the increased expression of ErbR in Trpc3−/− hearts under conditions of CIH may be a compensatory response of the heart to pulmonary hypertension resulting from impaired NO secretion." (PMID 37511045, 2023). "Human studies have also demonstrated elevated TRPC3 expression in the context of pulmonary arterial hypertension (PAH)." (PMID 42068376, 2026). "TRPC3 and TRPC6 are upregulated in idiopathic pulmonary hypertension and an siRNA-induced decrease of TRPC6 expression decreases proliferation of cultured pulmonary artery VSMC isolated from patients with pulmonary hypertension." (PMID 27037223, 2016).
status epilepticus (5 papers, 2020 to 2024). Status epilepticus is defined as a continuous seizure lasting more than 30 min, or two or more seizures without full recovery of consciousness between any of them. "Genetic ablation of TRPC3 channel expression reduced the intensity of pilocarpine-induced status epilepticus (SE)." (PMID 38892448, 2024). "In our study, we attempted to demonstrate the role of TRPC3 channels in pilocarpine-induced status epilepticus." (PMID 39408863, 2024). "We found that downregulation of TRPC3 channel-encoding genes reduced behavioral manifestations of seizures, indicating a significant contribution of TRPC3 channels to pilocarpine-induced status epilepticus." (PMID 39408863, 2024). "Using a TRPC3 global KO mouse line, we have demonstrated that genetic ablation of TRPC3 channels reduces behavioral manifestations of seizures and the root-mean-square power of SE, indicating a significant contribution of TRPC3 channels to pilocarpine-induced status epilepticus (SE)." (PMID 38892448, 2024).